OR4D11 (olfactory receptor family 4 subfamily D member 11)
Description:
Odorant receptor.
Synonyms: OR4D11P
Tractability: Antibody: UniProt places it where antibodies can reach, with medium confidence; UniProt predicts a signal peptide or a membrane-spanning region; its Gene Ontology location is reachable by antibodies, with medium confidence.
Gene: Protein-coding gene on chromosome 11 (59,503,576 to 59,504,511, forward strand). Ensembl gene ENSG00000176200.
Subcellular location: Cell membrane
Pathways (Reactome):
Sensory Perception: Expression and translocation of olfactory receptors
Gene Ontology:
Molecular function: olfactory receptor activity; G protein-coupled receptor activity
Biological process: detection of chemical stimulus involved in sensory perception of smell; G protein-coupled receptor signaling pathway
Cellular component: plasma membrane; membrane
Genetic constraint (gnomAD): Loss-of-function variants: 8 observed, 11.03 expected, observed/expected ratio (o/e) 0.73, 90% interval 0.43 to 1.31. The upper end of that interval is the gene's LOEUF score, 1.31, which puts it in group 5 of 6, group 1 being the genes least tolerant of losing a copy. Missense variants: 340 observed, 343.09 expected, observed/expected ratio (o/e) 0.99, 90% interval 0.91 to 1.08. Synonymous variants: 147 observed, 137.13 expected, observed/expected ratio (o/e) 1.07, 90% interval 0.94 to 1.23.
Homologues: Orthologues: chimpanzee OR4D11 (97% identical), macaque OR4D11 (94% identical), dog OR4D11 (90% identical), rabbit OR4D11 (90% identical), pig OR4D11 (89% identical), mouse Or4d11 (87% identical), rat Or4d11 (87% identical). Paralogues in human: OR4D9 (82% identical), OR4D10 (81% identical), OR4D6 (66% identical), OR4D1 (62% identical), OR4D2 (62% identical), OR4D5 (58% identical), OR4N5 (50% identical), OR4N2 (49% identical), OR4N4 (48% identical), OR4N4C (48% identical), OR4A47 (47% identical), OR4S2 (47% identical), and 116 more.